LGALS1 (galectin 1)
Diseases named in the same sentence as LGALS1 in open-access papers (continued):
Sharing a sentence is not in itself a finding about the gene and the disease.
tumor (continued). "The tumour ECM is remodelled at the protein level in MGUS and MM to allow development of a permissive microenvironment with two ECM-affiliated proteins, Annexin A2 (ANXA2) and Galectin-1 (LGALS1), more abundant in MM with high expression associated with inferior OS." (PMID 34556161, 2021). "Thus, a coordinated network of galectins, particularly galectin-1, -3, and -8 might regulate tumor proliferation by acting in both the extracellular and intracellular compartments." (PMID 35008740, 2021). "In addition, γδ TILs, in combination with galectin-1 antibody treatment, significantly suppressed the growth of tumor xenografts in severe combined immunodeficiency (SCID) mice (p < 0.05), although γδ TILs alone showed the ability to inhibit tumor growth in vivo." (PMID 34553029, 2021). "Tumor volumes (both for SiHa and C33A) were significantly higher in the LGALS1-Lt group than that in the control-Lt group from week 2 onwards (P <0.01), while apparently smaller in the LGALS1-shRNA group compared with the control-shRNA group from the 2nd weeks after inoculation (P <0.05)." (PMID 32047564, 2020). "However, galectin-1 is known to exert pleiotropic roles in the tumour microenvironment." (PMID 30813402, 2019). "IDO-positive tumor-associated vessels were studied by 7-color multiplex immunohistochemistry using the markers CD31/CD34 (endothelial cell markers), podoplanin (lymphatic endothelial cell marker), α-sma (perivascular cell marker), galectin-1 (activated endothelial cell marker), and IDO." (PMID 30050535, 2018). "Furthermore, co-cultivation of tumour cells and endothelial cells enhanced expression of Galectin-1 upon ionizing radiation, which might protect the tumour from radiation-induced cell death." (PMID 29498681, 2018). "Finally, because galectin-1, -3 and -9 have a role in tumor immune escape, we can suppose that targeting these galectins may restore the immune control of the disease." (PMID 29258207, 2017). "Moreover, galectin-1, -3 and -8 can support tumor cells migration and attachment to extracellular matrix (ECM) but the major role of galectin in the tumor progression is their interaction with the microenvironment, promoting neo-angiogenesis and inducing immune escape." (PMID 29258207, 2017). "In anti-VEGF refractory tumors, galectin-1 secretion increased together with its enhanced binding to neovascular endothelial cells due to altered glycosylation patterns on VEGFR2 (i.e., decreased α2,6-linked sialic acid), leading to galectin-1-driven angiogenesis and tumor progression." (PMID 29170525, 2017). "In addition, we have reported a further induction of galectin-1 expression in tumor stroma as a response to radiation therapy, suggesting that targeting galectin-1 may synergize with radiation therapy." (PMID 27223428, 2016). "Moreover, treatment of K562 cells with adriamycin or imatinib could increase galectin-1 expression, suggesting that tumor cells may gradually develop drug resistance along with the chemotherapy." (PMID 27050374, 2016). "In addition, galectin-1 is often overexpressed in the stroma surrounding tumor cells." (PMID 27649167, 2016). "However, there are few reports exploring the role of galectin-1 in tumor chemoresistance." (PMID 27050374, 2016). "Interestingly, our studies have revealed a further induction of the stromal galectin-1 in response to radiation exposure in 2D, 3D and various preclinical tumor models and, indicating the possibility of combining radiation with targeted nanochemotherapy and reduced side effects." (PMID 27223428, 2016). "Anti-VEGF-A refractory tumors enhanced galectin-1 secretion together with its increased binding to neovascular endothelial cells due to altered glycosylation patterns (i.e., decreased α2,6-linked sialic acid) on VEGFR2, leading to galectin-1-driven angiogenesis and tumor progression." (PMID 26648523, 2015).
tumor (continued). "Thus, this study revealed a novel mechanism by which the transcription factor LYAR may promote tumor cell migration and invasion by upregulating galectin-1 gene expression in CRC." (PMID 26413750, 2015). "Galectin 1 is a beta galactoside-binding protein which may be involved in tumour progression." (PMID 24229053, 2013). "Finally, galectin-1 induces apoptosis of activated T-cells, prevents host animals from mounting tumor vaccine-induced immunity, and may cooperate with TGF-beta in GBM-induced immunosuppression." (PMID 22583806, 2012). "The 2 to 4 fold change in galectin-1 mRNA expression at the tumor edge compared to core may not have been sufficient to cause a change in immunohistochemical staining." (PMID 22583806, 2012). "LGALS1 modulates the immune response and may contribute to immune privilege in tumours." (PMID 22279561, 2012). "Our observations support the idea that galectin-1 may contribute to immune privilege of tumours by modulating survival or polarisation of effector T cells, and suggest a potential molecular target for manipulation of T-cell apoptosis with potential implications in immunotherapy." (PMID 15785741, 2005). "Furthermore, galectin-1 can also regulate cell cycle progression in human tumour cells." (PMID 15785741, 2005). "Given the increased interest of tumour biologists and clinical oncologists in this field and the potential use of galectins as novel targets for anticancer drugs, we summarise here recent advances about the role of galectin-1 in different events of tumour growth and metastasis." (PMID 15785741, 2005). "Our findings align with previous work demonstrating that LGALS1, LGALS3, and LGALS9 bind to glycosylated ligands on T cells, inducing apoptotic cell death and attenuating anti-tumour immune responses." (PMID 41516291, 2025). "Concurrently, ADM can induce TREM2+ TAMs to release Galectin-1, reducing CXCL9 production thereby inhibiting CD8+ T cell tumor recruitment." (PMID 41450464, 2025). "If located on the cell surface, galectin-1 can introduce T cell apoptosis, so that SUSD2 contributes to the evasion of tumor cells from targeting by the immune system." (PMID 39890941, 2025). "The qRT-PCR results, based on 15 clinical GBM and paired non-tumor brain tissue samples, showed that the mRNA levels of ALOX5AP, LGALS1, and PLA2G5 were significantly higher in GBM tumor tissues compared to non-tumor brain tissues (all p < 0.05)." (PMID 41164132, 2025). "For example, Galectin-1 (LGALS1) was mainly expressed by fibroblasts, pericytes, and myeloid cells, all of which upregulate its expression in tumor compared to normal tissue." (PMID 38384845, 2024). "Galectin-1 and S100A4 were identified as upregulated proteins in the primary and secondary CT26 tumor tissues, and these were previously reported to contribute to the poor prognosis of CRC patients." (PMID 38612832, 2024). "We also identified galectin-1 as a critical role in the down-regulation of cell-surface CAR, which impairs the anti-tumor effect of CAR-T cells." (PMID 38184596, 2024). "Bioinformatics analysis revealed that APOC1, CFH, LGALS1 and NUSAP1 were highly expressed in bone metastases compared to primary tumours, whereas ADRB2, NR4A2 and ZNF331 exhibited the opposite trend (p < 0.05)." (PMID 39098992, 2024). "ZFP64 functions as a transcription factor that promotes the expression of Galectin-1 (GAL-1), contributing to stem-cell-like properties and an immunosuppressive tumor environment." (PMID 39185313, 2024). "This analysis led to the identification of genes generally associated with cancer cells (MUC1, LGALS3, UGDH, TSTA3, and GALE) or the stromal compartment (LGALS1, PSAP, LGALS9, IDS, and MGAT1) in most of the tumor types analyzed." (PMID 38384845, 2024). "The cellular anti-tumor immunity exhibited by CD8 cytotoxic T-cells is hampered by the expression of immunosuppressive mediators, such as PD-L1, CTLA-4, LAG-3, TIM-3, and galectin-1." (PMID 37515069, 2023).
tumor (continued). "Several cancers express galectin-1 (Gal-1), an immunosuppressive molecule that suppresses immune cell function in TME, contributing to tumor immune evasion." (PMID 37666809, 2023). "By analyzing datasets derived from The Cancer Genome Atlas (TCGA) database, we observed a significant positive correlation between LGALS1 and PDCD1 in five tumor types, with the exception of UCEC." (PMID 37833788, 2023). "Exogenous galectin-1 inhibited tumor cell–ECM adhesion and promoted tumor cell shedding through competitive binding with matrix glycoprotein or cell surface glycocomplex." (PMID 37328752, 2023). "Galectin-1 has also been found to bind to Neurophilin-1 (NRP-1), which serves as the VEGFR coreceptors in endothelial cells for tumour angiogenesis." (PMID 37371482, 2023). "Strikingly, although the reduction in tumor volume by 5 dpi was comparable for LBT070 and LBT070 LGALS1 KO (both ±75% reduction), LBT070 LGALS1 KO tumors were much more confined at 5 dpi than the invasive LBT070 tumors (Fig EV5D and E)." (PMID 37791581, 2023). "Most strikingly, our analysis revealed a seven-gene drug-tolerant signature in all four drug-tolerant cell lines, irrespective of chemotherapeutic treatment, parental cell line and tumour subgroup—LTBP1, MAP1A, MBNL2, LGALS1, PNRC1, DAB2 and PLAAT3." (PMID 36831428, 2023). "Tumor-infiltrating lymphocytes are often inactivated or exhausted due to immunosuppressive factors, including cytokines (IL-6, IL-10, TGF-β, galectin-1) secreted by tumor, stromal, and myeloid immune cells." (PMID 38087370, 2023). "Galectin-1 (Gal-1), a member of the galectin family, has emerged as a pivotal player in the PDAC microenvironment, influencing various aspects from tumor growth and angiogenesis to immune modulation." (PMID 37958483, 2023). "In another study, Kluza and coworkers showed that modification of liposomes with the two vascular targeting ligands galectin-1-specific anginex (Anx) and RGD results in enhanced specificity against tumor endothelium." (PMID 35214190, 2022). "Thus, while elevated expression in ESCC tumor tissues might underlie an increase in galectin-1 autoantibodies, the presence of these antibodies did not appear to be a valuable prognostic biomarker." (PMID 36497271, 2022). "They followed tumor development by re-transplanting tumor-isolated NES (tNES) cells in nude mice and identifying LGALS1 as a putative new therapeutic target." (PMID 35706426, 2022). "Galectin-1 inhibits the normal function of NK cells via multiple mechanisms, ultimately promoting PDAC tumor immune evasion." (PMID 36428567, 2022). "Galectin-1 stimulates IL-6, and IL-10 secretion in PDAC activates CAF expression and promotes stromal fibrosis of the tumor." (PMID 36428567, 2022). "In the hypoxic microenvironment, stable HIF-1α induces the expression of galectin-1 and glucose transporter-1 (GLUT1), which promote angiogenesis, tumor proliferation, and metastasis." (PMID 36428567, 2022). "In a mouse model, galectin-1 was reported to promote IL-10 secretion by PSC and induce fibrotic tumor stroma formation." (PMID 36428567, 2022). "While comparing with normal Tregs, tumor Tregs had increased expression of multiple genes related with immune suppression, including DUSP4, IL2RA, TNFRSF4, LAYN and LGALS1." (PMID 35664061, 2022). "The results showed that CAFs in P-LNs were associated with the high expression of NFIB, IGLC2, IGHG4, C7, and CCL19, while CAFs in tumor 3 had high expression of DIO2, LGALS1, WNT5A, NEAT1, and MMP11 in the tumor." (PMID 36569924, 2022). "Galectin-1 and galectin-3 make tumor cells prone to homologous aggregation, while CD47 allows tumor cells to escape phagocytosis by immune cells, thus improving tumor cell circulation in vivo." (PMID 36382024, 2022). "We found a high correlation of APOE, LGALS1, and PCSK1N, which were primarily expressed in SLS tumor cells, with macrophage frequency/activity in SLS-dominant tumors." (PMID 36028490, 2022).
tumor (continued). "Galectin-1 (GAL1), a β-galactoside-binding protein abundantly expressed in the tumor microenvironment, has emerged as a key mechanism of chemoresistance developed by different tumors." (PMID 35075112, 2022). "Galectin-1 has been found to accumulate in the stroma of HCC and is positively correlated with tumor size, stage, metastasis, low OS, and sorafenib resistance." (PMID 34552935, 2021). "Several potential biomarkers have been recently described such as a three-protein panel in urine, Galectin-1 (Gal-1) in serum, thrombospondin-2 (THBS2) in plasma, circulating tumor DNA (ctDNA), and the IMMrayTM PanCan-d 29 biomarker signature in serum." (PMID 33807330, 2021). "We further reported that LYAR promotes tumor cell migration and invasion by directly binding to the LYAR-binding motif (CTAACC; reverse complement GGTTAG) in the LGALS1 promoter to activate its expression in CRC cells." (PMID 35069968, 2021). "Galectin-1 derived from CAFs accelerates angiogenesis and promotes tumor invasion by enhancing VEGF expression in tumor cells and VEGFR2 phosphorylation in epithelial cells (ECs)." (PMID 34294146, 2021). "In early studies, galectin-1 expression correlated with the malignant potential of human GBM cells, and its prominent localization on the margins of these tumor cells contributed to delineate their invasive potential." (PMID 35008740, 2021). "Osteopontin, Galectin-1, and VEGF regulate many cellular processes, including cell proliferation, adhesion, tumor formation, migration, and angiogenesis." (PMID 34827604, 2021). "We observed that the expression of Galectin-1 (Gal-1), a soluble ligand of Neuropilin-1 (NRP1), is upregulated in melanoma tumor samples and melanoma cells resistant to BRAF-targeted therapy." (PMID 32784465, 2020). "The results were displayed a heatmap, which showed the expression levels of P3H1, SPP1, MMP1, LGALS1, and ITGB5 in tumor tissues and normal tissues." (PMID 32951492, 2020). "Lgals1 is a HIF-1-regulated gene and plays crucial pro-tumorigenic functions within the tumor microenvironment." (PMID 32785175, 2020). "FAM289-galectin-1 interaction and concomitant activation of the extracellular signal-regulated kinase (ERK) pathway participated in FAM289-mediated tumor-promoting function." (PMID 31492191, 2019). "Furthermore, CD117+ T cells are highly sensitive to apoptosis mediated by galectin-1, a molecule commonly expressed within the tumor microenvironment, and CD117 expression may therefore represent a novel and potentially targetable mechanism of tumor immune evasion." (PMID 30930902, 2019). "In all, Galectin-3 and Galectin-1 support high fidelity and prolonged Ras signaling downstream to Raf or PI3-kinase, and they also control Ras-regulated tumor suppressor, e.g., Bcl2 or β-catenin, thereby supporting tumor survival." (PMID 31861875, 2019). "For targeting tumor, peptides are commonly used to attach to proteins such as ανβ3-integrin, vascular endothelial growth factor receptor (VEGF-R), and galectin-1 which are overexpressed in both endothelial cells and a myriad of tumor cells." (PMID 30483904, 2018). "Galectin-1 confers drug resistance via inducing the expression of MDR protein 1, which in turn helps tumor cells to pump out cytotoxic drugs." (PMID 29389859, 2018). "However, in PDAC, galectin-1 could help tumor cells to escape from immune surveillance." (PMID 29254283, 2017). "Genes such as INHBA, IGF2, LGALS1, RHOJ, and THBS2 were upregulated in the tumor buds but downregulated in the microenvironment." (PMID 28687755, 2017). "Our study illustrates that TDEs are a mechanism used by multiple tumor cell lines to induce the formation of CD8+ Ts, especially through the presence of galectin-1 protein." (PMID 28806909, 2017).
tumor (continued). "Taken together, these results indicate that the high expression of galectin-1 in HSCs is correlated negatively with the reduced number of infiltrating CD3+ T cells and tumour development in HCC." (PMID 27494859, 2016). "ATP1B1, GPC3, KCNIP3, and PRLR transcript levels in tumor tissues were significantly lower in PTCs than in NT, whereas LCN2, LGALS1 and SCD1 expression was upregulated in PTC compared with NT." (PMID 27249794, 2016). "Galectin-1 is a beta-galactoside binding lectin which is up-regulated in HCC patients and promotes tumor growth by mediating cancer cell adhesion, migration and proliferation, but its role in chemoresistance of HCC is poorly understood." (PMID 26859293, 2016). "While galectin-1 is expressed in human HuH-7 cells, JHH-6 cells and tumour hepatocytes of human HCC tissue sections, galectin-1 levels in hepatocytes are significantly lower in HCC specimens than in normal liver and cirrhotic specimens." (PMID 27494859, 2016). "In this study we investigate the therapeutic outcome of radiation enhanced tumor-targeting of nanosized ATO and cisplatin chemotherapy to the galectin-1 enriched malignant stroma." (PMID 27223428, 2016). "Some clinicopathological features of HCC (including tumour size, differentiation, TNM stage and distant metastasis) were closely correlated with high galectin-1 expression and low CD3 expression in HSCs." (PMID 27494859, 2016). "Galectin-1, whose expression in SCLC in-situ correlates with the proliferation activity of tumor cells, was expressed by all cell lines." (PMID 24586258, 2014). "We evaluated the effects of PSCs derived Galectin-1 on the progression of PDAC, as well as the tumor establishment and development in mouse xenografts." (PMID 24595374, 2014). "The murine galectin-1 vaccine (TRX-mGal1) induces anti-Gal-1 antibodies, reducing tumor growth." (PMID 40134029, 2025). "The druggability of PDPN, PRSS3, GREM1, and LGALS1, alongside the established relevance of FAP, provides multiple entry points for stromal-directed interventions that could complement tumor cell–targeted therapies." (PMID 41198614, 2025). "Beyond FAP, signaling pathways such as Galectin-1 (Gal-1), the fibroblast growth factor receptor (FGFR)-Gremlin-1 axis, and glucocorticoid (GR) receptor signaling have emerged as key mediators of tumor–stroma crosstalk, particularly in treatment-resistant disease." (PMID 41198614, 2025). "Galectin-1 promotes angiogenesis by increasing CD31 and VEGF expression and enhancing endothelial cell proliferation, migration, and tube formation, thereby accelerating tumor growth." (PMID 40149995, 2025). "In this study, the expression of the tumor-suppressive CDK inhibitor p27 was increased, and the expression of oncogenic CDK2 and CDK4; cyclins (A, D, and E); and pRb was decreased by galectin-1 knockdown and miR-22-3p overexpression in primary hormone receptor-positive breast cancer cells." (PMID 39996781, 2025). "Mechanistically, LGALS1 may enhance the activity of the BCR downstream PI3K/AKT pathway, thereby inhibiting tumor cell apoptosis and promoting immune evasion." (PMID 41189944, 2025). "The induction of some proteins that were overexpressed in our CT26-bearing spleen model has been previously reported and it led to a poor prognosis in colorectal patients, such as Carbonic anhydrase IX (fold change tumor/control: FC: 26.155), protein S100A4 (FC: 23.44), and galectin-1 (FC: 10.25)." (PMID 38612832, 2024). "The presented data demonstrate that galectin-1, derived from MM, could mediate the tumor-promoting effect of M-MDSCs through its interaction with CD304 on M-MDSCs and contribute to tumor progression post-ASCT." (PMID 38464531, 2024). "In line with this, we were the first to show that galectin-1 is essential for tumor vascularization, independent of the tumor type." (PMID 38990363, 2024).